IL17A (interleukin 17A)
Diseases named in the same sentence as IL17A in open-access papers (continued):
Sharing a sentence is not in itself a finding about the gene and the disease.
colitis (continued). "Surprisingly however, blockade or genetic deletion of IL-17A resulted in aggravated disease severity in the DSS-induced colitis, a mouse model of IBD." (PMID 29118756, 2017). "Blocking IL-17A attenuated colitis and reduced tumor burden in APCmin/+ mice and AOM/DSS-treated mice." (PMID 28852270, 2017). "In the chronic TNBS induced colitis model, we found the colonic IL-17A was significantly increased in HSD TNBS treated mice as compared to the ND TNBS treated mice." (PMID 27926535, 2017). "In contrast to blockade of IL-17A, antibodies against IL-23 were effective in preventing colitis in mouse models." (PMID 29118756, 2017). "In contrast to these data, on day 10 after colitis induction, a decreased production of IL-17A and IFN-γ by colonic CD4+ T cells was detected in rel−/− mice in comparison to WT animals." (PMID 28881761, 2017). "The colitis mice given a neutralizing S100a9 antibody produced less inflammatory cytokines, such as Tnfα, Il1β, Il6, Il17a, Ifnγ, and Il12a, all of them are master regulators of inflammation and tumorigenesis." (PMID 29326691, 2017). "Recently, however, in vivo studies of an induced model of colitis have shown that IL-17A and IL-17F can have differing roles." (PMID 29311948, 2017). "MAM-secreting MG1363 markedly reduced the production of pro-inflammatory cytokines (IL-17A and interferon-γ) in the colonic tissue of colitis mice." (PMID 28179904, 2017). "Real time RT-PCR quantitation confirmed that pro-inflammatory cytokines and chemokines (CCL2, IL-1β, IL-6, IL-23, TNF-α, IL-17A and IL-17F) were elevated in quiescent and active colitis biopsies." (PMID 27271344, 2016). "Together, these data demonstrate that IL-23 is essential for the development of Hh-induced colitis and the emergence of IL-17A+IFN-γ+ T cells." (PMID 27193261, 2016). "By contrast with our results the Zimmerman study found that IL-17A blockade exacerbated colitis following transfer of Tbx21−/− T cells." (PMID 27193261, 2016). "We found that transfer of Tbx21−/− T cells induced IL-17A-dependent colitis despite increased frequencies of IL-4-expressing cells in the intestine." (PMID 27193261, 2016). "Strikingly, while RORγt is required for the differentiation of IFN-γ-producing Th17 cells and induction of colitis, T-bet is dispensable for the emergence of IL-17A+IFN-γ+ T cells and intestinal pathology." (PMID 27193261, 2016). "In fact, colonic CD4+ iELs of Il10−/− mice secrete elevated levels of IL-17A during colitis, which is enhanced by IL-23." (PMID 27027442, 2016). "Winnie mice progressively develop more severe colitis with age, which is accompanied by inflammation exemplified by progressively increasing Il17a." (PMID 27350069, 2016). "To examine the effects of MALT1 inhibitors on the cytokine expression in acute DSS colitis model, we measured the levels of IL-1β, IL-6, TNF, IFN-γ, IL-17A and IL-18 in colons of mice following induction of colitis and treatments with MALT1 inhibitors." (PMID 27105502, 2016). "In the same way, the Th17 lineage is required for protection against C. rodentium, but Il17a−/− mice show reduced severity of colitis in the DSS model." (PMID 27783672, 2016). "infantis JCM 1222 has been shown to directly act on IECs to suppress CD80 and CD40 expression, and subsequently resulting in the suppression of mRNA and protein expression levels of IL-17A and alleviation of colitis." (PMID 26340622, 2015). "It was also revealed that murine DSS-induced colitis was worsened in IL-17A-knockout mice but was substantially improved in IL-17F-knockout mice." (PMID 26340622, 2015). "Circulating IL-17A levels increased only in mice with colitis exposed to WAS, which indicates that stress can promote cytokine formation." (PMID 26066467, 2015). "Along this line, the contribution of Lin-Thy+ILC3 secreting IL-17A was described in colitis of Tbet-/-Rag-/- (TRUC) mice." (PMID 25853847, 2015).
colitis (continued). "The level of IL-17A is positively correlated with the severity of CD, while IL-17A deficiency is associated with resistance to colitis development, suggesting that IL-17A promotes colitis." (PMID 26347488, 2015). "This is consistent with a previous report of diminished serum IL-6 and IL-17A levels in cd47-/- mice in a dextran sulfate-induced colitis model." (PMID 26010544, 2015). "IFN-γ and IL-17A are the key cytokines for Th1 and Th17 responses and are also thought to play pathogenic roles in CD and the chronic stage of DSS-induced colitis." (PMID 26161006, 2015). "In animal studies, a protective role was suggested for IL-17A in a T-cell transfer model of colitis." (PMID 26340622, 2015). "Meanwhile, Rag1−/− hosts transferred with IL-17A−/− CD4+ CD45RBhigh T cells show more severe colitis compared to Rag1−/− mice received corresponding wild type CD4+ T cells, accompanying by increased IFN-γ level in colon." (PMID 25133396, 2014). "Whereas murine DSS-induced colitis was worsened in IL-17A KO mice, a clear improvement of the colonic inflammatory process was observed in IL-17F KO mice." (PMID 25101191, 2014). "Our data suggest that IL-17A plays a different role in autoimmune cholangitis and colitis and raises concerns and caution regarding the therapeutic use of anti-IL-17A." (PMID 25133396, 2014). "Of note, deletion of IL-17A in IL-2Rα−/− mice led to more severe liver inflammation, but ameliorated colitis." (PMID 25133396, 2014). "Actually, the amounts of IL-6 and IL-17A secreted from the GPx1−/− × Cat−/− splenocytes were much less than those from WT splenocytes in DSS-induced colitis." (PMID 24743300, 2014). "Here CECs were selected as the target for IL-17A, as we previously found that, in mice with TNBS-induced colitis, expression of IL-17A in and IL-17RA on CECs was significantly increased." (PMID 24586980, 2014). "On the protein level, ELISA analysis of colon supernatants demonstrated increased concentrations of IFN-γ, IL-17A and IL-10 in the colons of mice with colitis." (PMID 25313594, 2014). "Systemically, CBA analysis showed that the concentrations of IFN-γ and IL-17A were increased in the serum of mice with colitis." (PMID 25313594, 2014). "To examine in specific detail the role of IFN-γ versus IL-17A in autoimmune cholangitis and colitis, we took advantage of IL-17A−/−IL-2Rα−/− and IFN-γ−/−IL-2Rα−/− mice." (PMID 25133396, 2014). "The rapidly proliferating naïve donor VDR KO CD8+ T cells found residence in the MLN first and then in the IEL of the Rag KO mice where they out-competed the CD4+ T cells and contributed to colitis development by inducing IL-17A and IFN-γ production." (PMID 24502291, 2014). "Colitis, however, was improved in IL-17A−/−IL-2Rα−/− mice compared to IL-2Rα−/− mice (P<0.05), although minimal colitis still occurred in IL-17A−/−IL-2Rα−/− mice." (PMID 25133396, 2014). "Our results demonstrate that helminth antigen-induced amelioration of experimental colitis is associated with a downregulation of the proinflammatory cytokines IFN-γ and IL-17A and the upregulation of the anti-inflammatory cytokine IL-4 in the colon." (PMID 25313594, 2014). "Our data suggests that IL-17A plays a protective role in autoimmune cholangitis but a proinflammatory role in colitis in IL-2Rα−/− mice." (PMID 25133396, 2014). "We report herein that deletion of IL-17A in IL-2Rα−/− mice aggravated cholangitis but ameliorated colitis." (PMID 25133396, 2014). "Physical and histopathological examination of colon tissue revealed marked tissue injury and infiltration of inflammatory cells in TNBS colitis mice receiving anti-IL-17A antibody." (PMID 24586980, 2014). "In models of colitis driven by IL-17A+ or IL-17A+IFN-γ+ T cells, suppression of disease by Foxp3+ Treg or Tr1 cells required direct IL-10 signaling into the effector T cells." (PMID 23405904, 2013). "In conclusion, this study demonstrated that JCM 1222T suppressed intestinal IL-17A response in DSS-induced colitis." (PMID 24255712, 2013).
colitis (continued). "The leukocyte infiltration into the mucosa and submucosa of the small intestine of mice with colitis at 6 DPI was associated with increased concentration of IL-6, IL-12p70, IL-10, IL-22 MCP-1 and TNF-α, IL-1β, MPO but lower concentration of IL-17A." (PMID 24167594, 2013). "A recent study demonstrated that intestinal epithelial cell-specific STAT3 deficiency results in altered STAT3 activation in the immune cells and the expansion of IL-17A-secreting intestinal T cells in a colitis model." (PMID 23950992, 2013). "We show here that JCM 1222T negatively regulates the expression of intestinal epithelial costimulatory molecules, resulting in the suppression of IL-17A response and colitis." (PMID 24255712, 2013). "In contrast, anti-IL-17A monoclonal antibody treatment was demonstrated to aggravate dextran sulfate sodium-induced colitis, and blockade of IL-17A in colitis of IL-10 knockout mice was inefficient in reducing disease unless IL-6 was also neutralized." (PMID 23956763, 2013). "Studies in animal models of trinitro-benzene-sulfonic acid-induced colitis and concanavalin A (Con A)-induced hepatitis indicated that the blockade of IL-17A by IL-17R: FC is dependent primarily on the downregulation of IL-6 and TNF-α." (PMID 23977238, 2013). "Interleukin-17A has been shown to prevent Th1 immune response in the CD45RB transfer model of colitis." (PMID 24146810, 2013). "In contrast to control antibody treatment, administration of a neutralizing IL-17A antibody markedly improved colitis." (PMID 23063332, 2012). "It is also remarkable that the shift from IL-17A into IFN-γ production in the colonic mucosa of IL-10−/− mice coincided with more severe colitis, spreading of inflammation to the small intestine and deterioration in the clinical status of the animals." (PMID 22400037, 2012). "TNBS-induced colonic inflammation in mice is a commonly used chemically induced model that features up-regulation of pro-inflammatory cytokines (IL-1β, IFNγ, TNFα, IL-12, IL-17A)." (PMID 22461841, 2012). "In this regard, Yang and colleagues showed that murine DSS-induced colitis was worsened in IL-17A knockout (KO) mice but significantly improved in IL-17F KO mice." (PMID 22506136, 2012). "It is probable that the IL-17 R KO mice would not respond to either IL-17A or IL-17F, suggesting that inhibition of both forms of IL-17 is needed for attenuation of colitis." (PMID 22506136, 2012). "Conversely, a different study reported that genetic inactivation of IL-17A substantially reduces colitis based on both clinical score and mortality compared to WT animals, suggesting that IL-17 promotes colitis." (PMID 22229105, 2012). "Lastly, since the presence of Itk helps to promote IL-17A production, the recent finding that IL-17A provides a protective function in a colitis model system suggests that Itk too can be important in the mediation of intestinal inflammation." (PMID 21747996, 2011). "Mice deficient in IL-17A gene, showed only faint manifestations of colitis thereby suggesting that IL-17A plays a pivotal role in the pathogenesis of DSS-induced colitis." (PMID 21858153, 2011). "Recent findings revealed that SBAs are dedicated to the remission of murine colitis, as 12-ketolithocholic acid could inhibit the secretion of IL-17A by type 3 innate lymphoid cells (ILC3) through upregulating Vitamin D receptor (VDR)." (PMID 40612235, 2025). "Depletion of all ILCs or neutralization of IL-17A improves colitis in such a model." (PMID 41194916, 2025). "In conclusion, DBK successfully reduced inflammation in DSS-induced UC mice by modulating the IL-6/IL-6R and IL-17A/IL-17RA pathways, as evidenced by alleviated colitis symptoms, decreased pro-inflammatory cytokines (TNF-α, IL-6, IL-1β), and histological improvements." (PMID 40005956, 2025).
colitis (continued). "Treatment with an IL-17A antibody leads to the diffusion of occludin, compromising intestinal integrity, increasing gut permeability, facilitating pathogen invasion, and ultimately exacerbating colitis through the altered localization of occludin." (PMID 39379604, 2024). "To investigate the role of mPGES-1 in the development of Th17/Th1 immune responses involved in colitis, we next analyzed the proportions of Th17 and Th1 cells that produced IL-17A and IFNγ in mesenteric lymph nodes (MLNs) of mPGES-1−/− and WT mice following colitis induction." (PMID 39596393, 2024). "However, previous results found that the expression of IL-17A is important for orchestrating early inflammatory responses during S. Typhimurium colitis." (PMID 39435479, 2024). "After DSS treatment, ILC3s primarily produce IL-22 rather than IL-17.28,67 Our data align with these findings, highlighting the beneficial roles of C. tropicalis induced IL-17A and IL-22 and the crosstalk between fungal intestinal colonization and host immune response in ameliorating colitis." (PMID 39462273, 2024). "Indeed, blockade of both IL-17A and IL-17F ameliorates colitis, while inhibition of only IL-17A is insufficient." (PMID 39379604, 2024). "Also, L. lactis was successful in transferring IL-17A in cancer mouse model, Heme oxygenase-1 in mice with colitis, and hTFF1 in hamster with oral mucositis." (PMID 38495751, 2024). "This dichotomy, despite both IL-17A and IL-17F acting on the same receptor, implies that each may play distinct roles in the initiation and progression of colitis." (PMID 39379604, 2024). "However, the absence of TIGIT protected mouse from Dextran Sodium Sulfate (DSS)-induced colitis through the regulating IL17A-producing tissue-resident memory T cells." (PMID 38545097, 2024). "In addition, FexD largely blocked the colitis-induced increases of IL17A+ and IFN-γ+ in CD4+ T cells and IFN-γ+ in CD8+ T cells in both ileal and colonic lamina propria." (PMID 38258906, 2024). "However, similar cases of new-onset colitis during IL-17A-inhibitor therapy and data suggesting paradoxical colitis activity in Crohn’s disease patients raise concerns." (PMID 38060157, 2024). "Elevated levels of IL-17A have been identified in mouse colitis induced by TNBS or CR." (PMID 37111225, 2023). "And then, we found that the oral administration of 12-KLCA, a derivate of LCA that is very little in SUCs and their recipient mice, could exert an anti-inflammatory effect on experimental colitis through the inhibition of IL-17A secreted by ILC3s." (PMID 38062857, 2023). "While the colitis-induced IL-17A showed minor effects on the recipient-derived CD8+ T cells." (PMID 37605139, 2023). "In line with the results of network pharmacology approach, in vivo studies confirmed that FC alleviated DSS-induced colitis, reduced systemic inflammatory response, and diminished the expression of IL-17 signaling pathway mediators, IL-17A, RORγt, and tissue remodeling factors MMP1, MMP3 and MMP9." (PMID 37161415, 2023). "Colitis mice also displayed IL-17A elevation in blood, but increased 2-folds only." (PMID 37605139, 2023). "IFNγ and/or IL-17 A production by T cells is necessary for colitis development." (PMID 38012544, 2023). "In addition to increased G-CSF and MIP-3α in the lungs of TCRδ-/- mice with colitis, IL-17A is likely contributing to increased neutrophil recruitment to the lungs as has been observed in other models of lung inflammation." (PMID 37063825, 2023). "Therefore, we investigate if AhR orchestrates the effects of combined butyrate and VD3 on cytokines response (IL-17A and IL-22), antimicrobial peptides (LL-37), and tight junction proteins expression to block the invasion of Salmonella in colitis mice." (PMID 36678175, 2023). "In conclusion, B cells play a protective role in ETBF-induced colitis, and IL-17A inflammation is not attributed to prompted colitis in B-cell-deficient mice." (PMID 38203534, 2023).
colitis (continued). "We further investigated the function of IL-17A/IL-17F in DSS-induced colitis mouse model." (PMID 36792629, 2023). "The role of TH17 and IL-17A in the pathogenesis of colitis is still controversial." (PMID 37436991, 2023). "In contrast, the alleviation of DSS-induced colitis progression in Nsun2cKO mice could be reversed by injecting recombinant mouse-IL-17A (rIL-17A), IL-17F (rIL-17F), or both." (PMID 36792629, 2023). "Moreover, we showed that L. johnsonii N5 treatment balanced the intestinal PP Treg/Th17 responses by increasing Treg cell numbers and suppressing the Th17 population and its IL-17a production under physiological condition, as well as during colitis." (PMID 38033603, 2023). "Deletion of Bcl6 results in dysregulation of the LTi-like ILC3 transcriptional program and markedly enhances expression of IL-17A and IL-17F in LTi-like ILC3, in a manner in part dependent upon the commensal microbiota - and associated with worsened inflammation in a model of colitis." (PMID 37950867, 2023). "Mice with colitis treated with PPIs showed an increase in the expression of pro-inflammatory cytokines such as IL-1β, IL-6, interleukin-17A (IL-17A), TNF-α, interferon-γ ( IFN-γ), macrophage inflammatory protein-2 (MIP-2), and monocyte chemotactic protein-1 (MCP-1)." (PMID 37142877, 2023). "In addition, ETBF-mediated colitis persists, leading to synchronized expansion of IL-17A-producing inflammatory Th17 cells/γδ T cells and immune-suppressive FoxP3+ T-cells (Tregs) in the large intestine of mice." (PMID 38203534, 2023). "In DSS-induced colitis in experimental mice, IL-17A is critical in regulating inflammation." (PMID 37047133, 2023). "Notably, IL-17A expression was largely increased in all the three subsets of CD4+ T cells during DSS-induced colitis." (PMID 35844584, 2022). "Interestingly, IL-21 signalling was recently proposed to dampen T-cell transfer colitis by reducing IL-17A production and augmenting IL-22 production in populations of ILC3s." (PMID 36012618, 2022). "IL17A inhibits spontaneous colitis in IL10-/- mice via the inducible nitric oxide synthase pathway." (PMID 35546404, 2022). "Previous studies on mouse colitis have found that IL-1β is significantly increased when intestinal inflammation occurs, which mediates chronic intestinal inflammation by promoting the accumulation of IL-17A-secreting innate lymphoid cells and Th17 cells." (PMID 35265068, 2022). "CD4+ T cell–derived cytokines such as IL-17A and IFNγ are pro-inflammatory and have been shown to be pathogenic in murine models and in patients with IBD, whereas Treg cells protect mice from DSS-induced colitis." (PMID 35844584, 2022). "Besides, LUT@TPGS-PBTE NPs most effectively inhibited the percentage of Th17 ​cells and suppress the levels of IL-17A protein and mRNA secreted by Th17 in the colitis mice." (PMID 35372817, 2022). "It was shown in a trinitrobenzene sulfonic acid (TNBS) and dextran sodium sulfate (DSS)-induced colitis model that overexpression of elafin led to restoration of proteolytic balance; downregulation of IL-6, IL-8, IL-17A, and NFκΒ; and inhibition of TNF-α–induced increased permeability." (PMID 36552023, 2022). "The CBM intervention on AOM/DSS mice failed to improve colitis and colitis-associated neoplasms but changed microbial composition and unexpectedly increased expression of proinflammatory IL-17A in rectal tissue." (PMID 36077084, 2022). "Altogether, the increased mTOR activity caused by TSC1 deficiency in macrophages might contribute to the accelerated DSS-induced colitis in TSC1cKO mice and high expression of IL-17A, IL-17F, and IFN-γ in macrophages." (PMID 36465179, 2022). "Furthermore, deficiency in ubiquitin ligase Itch leads to spontaneous colitis and increased susceptibility to CRC through the release of RORγt degradation and excessive production of IL-17A." (PMID 35967333, 2022).